Y_RNA (Y RNA )
Gene: Miscellaneous RNA gene on chromosome 18 (12,760,717 to 12,760,818, forward strand). Ensembl gene ENSG00000201466.
Homologues: Orthologues: chimpanzee Y_RNA (99% identical), guinea pig Y_RNA (93% identical), macaque Y_RNA (91% identical). Paralogues in human: Y_RNA (89% identical), RNY3 (88% identical), Y_RNA (88% identical), Y_RNA (87% identical), Y_RNA (86% identical), RNY3P1 (85% identical), RNY3P16 (85% identical), Y_RNA (85% identical), Y_RNA (84% identical), RNY3P14 (83% identical), Y_RNA (83% identical), RNY3P3 (82% identical), and 93 more.